INS (insulin)
Diseases named in the same sentence as INS in open-access papers (continued):
Sharing a sentence is not in itself a finding about the gene and the disease.
Hyperglycemia (continued). "However, the failure of the INS1R, referred to as insulin resistance, leads to increased insulin secretion (hyperinsulinemia) and failed blood sugar level regulation, resulting in severe symptoms of hyperglycemia." (PMID 39378614, 2024). "Moreover, ZLN005 has been shown to increase fat oxidation and improve glucose tolerance, pyruvate tolerance, and insulin sensitivity in diabetic mice, and suppress hyperglycemia-induced cardiomyocyte injury." (PMID 39273020, 2024). "Previous findings indicate that higher doses of 2-DG may lead to transient hyperglycemia or insulin responses, which could diminish its effective concentration at the target site." (PMID 39703288, 2024). "Understanding exercise-induced changes in systemic inflammation, hyperglycemia and insulin sensitivity as well as anabolic and anti-catabolic actions will aid in optimizing exercise training delivery to better target postburn muscle wasting and related metabolic morbidity." (PMID 38716050, 2024). "Hyperglycemia-mediated activation of mTOR in the cardiovascular system has also been associated with cardiac and vascular remodeling and dysfunction that lead to DCM due to decreased insulin signaling." (PMID 39239455, 2024). "Interestingly, in our high-dose FO and OO high-fat dietary intervention experiments, both OO, and FO ameliorated hyperglycemia and hyperinsulinemia, increased insulin sensitivity, and modulated dyslipidemia in obese mice." (PMID 38501107, 2024). "Conditional knockout of Madd in mouse β cells leads to hyperglycemia, glucose intolerance, and reduced and delayed glucose-induced insulin release, and rhythmic alternative splicing of Madd transcript regulates glucose-stimulated insulin secretion in mouse β cells." (PMID 38775154, 2024). "However, GMP supplementation significantly limited hyperglycemia and hyperinsulinemia, suggesting that these animals were better able to respond to insulin signals and more effectively control carbohydrate metabolism." (PMID 38542783, 2024). "The extract was speculated to have improved hyperglycemia by enhancing insulin sensitivity and glucose uptake or modulating glucose metabolism pathways." (PMID 38931040, 2024). "In the perioperative period, literature suggests minimizing pre-surgical fasting with close monitoring of leucine, pH, glucose, fluid, and electrolytes, as insulin can redistribute, to diminish catabolic stress response with resultant hyperleucinemia and hyperglycemia." (PMID 39347258, 2024). "Rebound hyperglycemia following the resolution of diabetic ketoacidosis (DKA) is common in pediatric patients with type 1 diabetes, increasing the risk of recurrent DKA and complicating the transition to subcutaneous insulin." (PMID 39136541, 2024). "Persistent hyperglycemia and excess insulin administration during diabetic ketoacidosis treatment in type 1 DM are hypothesized to be metabolic preconditions for glycogen deposition in the liver which can damage hepatocytes." (PMID 38756113, 2024). "Hyperglycemia and dysregulation of insulin action may contribute to amyloid plaque formation and neurodegeneration." (PMID 39493064, 2024). "In contrast, insulin may stimulate greater glucose transport to the brain in insulin-resistant patients during hyperglycemia." (PMID 37611907, 2024). "This suggests that systemic hyperglycemia alone can trigger insulin signaling in GBM." (PMID 38396649, 2024). "However focusing on hyperglycemia that defines T2DM is mainly secondary to inadequate action of the primary glucose-lowering hormone insulin." (PMID 38799166, 2024). "Failure to respond to insulin thus may exacerbate hyperglycemia as glycogenolysis, and hepatic gluconeogenesis may persist even as the blood glucose levels are already elevated." (PMID 38398503, 2024). "Rapid overcorrection of hyperglycemia with insulin can result in CE, seizures, and even death." (PMID 39360087, 2024).
Hyperglycemia (continued). "The absence of Rab3a in mice was shown to lead to severe hyperglycemia and insulin secretory deficiencies (Varadi, Tsuboi, and Rutter, 2005)." (PMID 38606007, 2024). "This might be due to gradual impairment of insulin secretion by beta-cell as a result of the compensatory response of hyperglycemia, increase in insulin resistance and beta-cell of the pancreas may be damaged." (PMID 38962352, 2024). "have succeeded in decreasing hyperglycemia and increasing insulin level in diabetic treated group." (PMID 38461158, 2024). "This destruction results in decreased insulin secretion and thus hyperglycemia." (PMID 39139674, 2024). "Similarly, insulin and resveratrol therapy, green tea intake reduced hyperglycaemia in diabetic mice." (PMID 38700145, 2024). "Several environmental and genetic factors might lead to impaired insulin production by pancreatic β-cells and impaired insulin sensitivity in tissues, resulting in the clinical manifestation of hyperglycemia." (PMID 38539811, 2024). "The percentage of cases with an adequate response to hyperglycaemia (glucose level >200 mg/dL) or hypoglycaemia (glucose level <60 mg/dL), involving the administration of insulin or glucose, respectively, and recheck was comparable for both sexes (aOR: 0.9970; 95% CI 0.9901–1.0038)." (PMID 39598129, 2024). "TH mice are also classified as insulin-resistant and hyperglycemia-induced obesity models." (PMID 39273348, 2024). "The resulting alterations in hormone secretion, substrate availability, and nutrient signaling could undermine insulin sensitivity and pancreatic β-cell function, contributing to hyperglycemia and the pathogenesis of GDM." (PMID 38248846, 2024). "Third, glucose is usually absorbed across cell membranes via carrier-mediated facilitated transport systems, and glucocorticoids inhibit glucose transporter 4 (GLUT4), thereby impairing insulin-mediated glucose uptake in skeletal muscle and indirectly promoting the occurrence of hyperglycemia." (PMID 38725059, 2024). "The activity of different phytocompounds present in PHE may reduce hyperglycemia by one of several mechanisms, including repair of β-cell proliferation, stimulation of insulin production, and augmentation of insulin effects." (PMID 38234664, 2024). "Hyperglycemia triggers β-cell insulin release and suppression of α-cell glucagon secretion." (PMID 39619323, 2024). "Inpatient CDS systems are being designed to integrate with electronic medical records (EMRs) and thus reduce scenarios of severe hypoglycaemia and recurrent hyperglycaemia, while minimising inappropriate use of insulin therapy that might lead to harm." (PMID 38953925, 2024). "Moreover, GLP-1 has a direct impact on pancreatic β-cells within the islets of Langerhans, stimulating insulin secretion and reducing glucagon release, which collectively helps to maintain glucose homeostasis and protect against postprandial hyperglycemia." (PMID 39518431, 2024). "During initiation or intensification of Insulin therapy in those with chronic hyperglycemia, peripheral edema may ensue in a condition known as insulin edema syndrome." (PMID 38435190, 2024). "Meanwhile, rising gluconeogenesis maintains blood glucose levels above the starvation range, and subsequent recovery of insulin sensitivity may further limit hyperglycemia." (PMID 39781139, 2024). "Although treat-to-target insulin is recommended in general to correct hyperglycemia, it remains unclear which treatment strategy has a positive effect on outcomes." (PMID 38281042, 2024). "Routine monitoring of blood glucose levels was viewed as critical for the early detection and treatment of chemotherapy-induced hyperglycemia by allowing for a prompt adjustment of insulin or other anti-hyperglycemic medications, while minimizing the risk of hypoglycemia or other side effects." (PMID 39088060, 2024).
Hyperglycemia (continued). "In response to hyperglycemia and to compensate for insulin resistance, insulin levels may initially rise, promoting further intracellular potassium shift and potentially leading to hypokalaemia." (PMID 38993410, 2024). "This is in accordance with other studies regarding the idea that natural plant extracts may ameliorate hyperglycemia and insulin sensitivity." (PMID 39063332, 2024). "Intermediate-acting insulin may be equally effective to basal-bolus insulin in reducing GC-induced hyperglycemia and preventing hypoglycemic events." (PMID 38281042, 2024). "Homogeneous distribution of insulin.Hydrogel possessed glucose-dependent volume change for insulin release in hyperglycemia and was silenced when glucose concentration decreased.Negligible temperature dependency for insulin release.Long-lasting release of insulin for several days (78 h)." (PMID 38147499, 2024). "The Alloxan model of hyperglycemia could result in the partial (or total, dose‐ and time‐dependent) destruction of the β‐cells of the pancreas and a decline in serum levels of insulin because of decreased synthesis." (PMID 39055210, 2024). "Additionally, peripheral tissues become resistant to insulin due to impaired insulin-signalling pathways, leading to high levels of glucose in the bloodstream, or hyperglycaemia." (PMID 39458491, 2024). "This stimulates insulin release, resulting in a reduction in post-prandial hyperglycemia." (PMID 38892604, 2024). "We demonstrate here that in ZCL rats, INS-DF elevates EGP and PG levels toward those seen in ZDF rats even with GCG-DF, suggesting a dominant role of insulin resistance to cause an elevation of EGP and hyperglycemia." (PMID 38265288, 2024). "- If symptomatic hyperglycemia, HbA1c >10% and/or blood glucose >300 mg/dL (signs of marked insulin deficiency).- Patients on treatment with 3-4 non-insulin therapies that do not reach glycemic targets." (PMID 38559691, 2024). "The persistent hyperglycemia results in an increased insulin requirement usually up to four times." (PMID 38255714, 2024). "Finally, we investigated the therapeutic potential of EMCVIRES-based insulin secretion circuits in reversing Hyperglycaemia in T1D mice." (PMID 39279997, 2024). "Insulin is involved in regulating renal glucose metabolism, as hyperglycemia may lead to the development of diabetic kidney diseases (DKDs)." (PMID 38397072, 2024). "Hyperglycaemia may be related to impaired glucose-stimulated insulin secretion by pancreatic β-cells, leading to reduced uptake of glucose." (PMID 38365697, 2024). "However, early and late administration of WJMSCs-CM to diabetic animals reduced hyperglycemia and enhanced insulin production." (PMID 39391856, 2024). "Furthermore, catecholamine use has been associated with immunosuppression, bacterial growth, increased bacterial virulence, biofilm formation, insulin resistance, and hyperglycemia." (PMID 38184601, 2024). "Emerging evidence suggests that 25(OH)D supplementation in pregnant women might regulate metabolic alteration, including hyperglycemia by improving insulin sensitivity." (PMID 38882352, 2024). "Moreover, in specific patient subgroups, early initiation of insulin is crucial for hyperglycemia control and prevention of chronic complications." (PMID 38559691, 2024). "Bmal1 or Clock mutant mice exhibit T2D symptoms, including hyperglycemia and lower insulin levels." (PMID 39165284, 2024). "This suggested the correlation between the cause of hyperglycemia in βKO mice and impaired pancreatic β-cell function and insulin secretion dysfunction rather than peripheral tissue insulin resistance." (PMID 38904034, 2024). "By blocking this receptor, teprotumumab may impair the ability of insulin to lower blood glucose levels, resulting in hyperglycemia." (PMID 39185318, 2024).
Hyperglycemia (continued). "Therefore, the multifaceted benefits of exercise extend beyond insulin sensitivity, encompassing the mitigation of hyperglycemia-related pathways to safeguard cognitive function in individuals living with T2DM." (PMID 38900771, 2024). "In the SHINE (Stroke Hyperglycemia Insulin Network Effort) trial, the patients were randomly selected to follow the therapeutic modalities of continuous intravenous insulin (intensive glucose control) or subcutaneous insulin on a sliding scale (standard glucose control) for up to 72 h." (PMID 39407846, 2024). "Transient hyperglycemia occurs, and more insulin is secreted." (PMID 38952701, 2024). "It is noteworthy that sustained hyperglycemia may result in elevated insulin levels, raising concerns regarding the stability of blood glucose levels." (PMID 39080776, 2024). "This subsequently leads to the requirement for insulin to normalize fasting hyperglycemia." (PMID 39902162, 2024). "Since insulin plays a crucial role in cell glucose entry, any disruption in insulin signal transduction interferes with glucose uptake by the cells, thus leading to hyperglycaemia." (PMID 38953241, 2024). "Interestingly, ER which is an integral machinery site for the synthesis of insulin in the pancreatic β cells is highly sensitive to hyperglycaemia‐induced oxidative stress." (PMID 39656379, 2024). "This may reflect a time lag in either the hyperglycemia or the corticosterone stimulation of insulin secretion." (PMID 38473137, 2024). "Insulin tended to be higher in this group (though significant difference was not reached), suggesting still partial compensatory augmentation of insulin secretion to counterbalance hyperglycemia." (PMID 38681771, 2024). "Further adjustments in insulin dosages or consideration of additional therapeutic modalities may be warranted to address persistent postprandial hyperglycemia." (PMID 38542117, 2024). "Primary insulin deficiency resulting in hyperglycaemia may lead to a relative reduction in insulin sensitivity, possibly due to hyperglycaemia or due to a delayed and mismatched insulin secretion." (PMID 39093413, 2024). "From a pathophysiological point of view, patients at high risk for developing PTDM may benefit from intensive treatment of hyperglycemia over the insulin secretion axis." (PMID 38397919, 2024). "hBMSC overexpressing the angiogenic factor VEGF, exhibited a sustained potential to reverse hyperglycemia in diabetic mice which was correlated with the activation of insulin/insulin-like growth factor (IGF) receptor signaling pathway involved in maintaining beta-cell mass and function." (PMID 39468609, 2024). "If the user is unsatisfied with the amount of insulin, an alternative lower glucose target value can be entered to increase the dose besides using a “Boost” feature, meaning that the algorithm will deliver approximately 35% more insulin if hyperglycemia is experienced." (PMID 38785359, 2024). "In conclusion, this study suggests that silibinin could have positive effects on diabetic rats in terms of hyperglycemia, insulin levels, liver function test parameters, and behaviors such as learning and locomotor activity." (PMID 38726421, 2024). "Hyperglycemia requiring insulin (>10 mmol/L) occurred in 92 patients (28.5%)." (PMID 39064465, 2024). "However, despite the effectiveness of insulin injections in managing hyperglycemia, they fall short in addressing autoimmunity and regenerating damaged islets, which are crucial in type 1 diabetes management." (PMID 39120188, 2024). "Critically ill patients often have hyperglycemia because of impaired insulin activity; however, whether low BMP6 levels of patients with sepsis/septic shock contribute to metabolic pathophysiology in these patients requires further study." (PMID 39200147, 2024).
Hyperglycemia (continued). "A substantial number of studies have demonstrated that treatment with fucoidan (extracted from various algal sources) is effective in lowering hyperglycaemia, regulating glucose metabolism, increasing insulin production, and alleviating pancreatic β-cell damage." (PMID 38786601, 2024). "Tacrolimus may lead to hyperglycemia by affecting insulin secretion and altering tissue sensitivity to insulin." (PMID 38774214, 2024). "Clinically, the manifestation of T2DM is seen as chronically elevated blood glucose levels or hyperglycemia due to the inability of pancreatic β-cells to adequately produce/secrete glucose-regulating hormone, insulin, and/or the insulin resistance of peripheral tissues." (PMID 39273561, 2024). "In diabetic mice, this was found to be exerted through a reduction in hyperglycemia, the inhibition of gluconeogenesis, increases in glycogen and insulin, and the regeneration of injured β-cells, with decreased levels of glycosylated hemoglobin (HbA1C) also being reported." (PMID 39683371, 2024). "Similarly, treating hyperglycaemia was accelerated by giving insulin within one hour from first elevated glucose level (adjusted increase of 14%)." (PMID 39420409, 2024). "Patients with postprandial hyperglycemia consume food with reduced insulin secretion and reduced inhibition of glucagon release, which leads to abnormal glucose levels in the liver and kidneys, reduced glucose uptake by cells, and increased blood glucose levels." (PMID 39596859, 2024). "Collectively, our results demonstrate that Cytopore I-encapsulated EMCVIns implants are capable of uninterrupted insulin secretion, which may contribute to the reversal of hyperglycemia and the potential achievement of long-term blood glucose homeostasis." (PMID 39279997, 2024). "IR is a pathophysiological disorder that manifests itself primarily in the form of decreased insulin sensitivity of muscle and liver tissues, resulting in a reduced bioavailability of insulin, a diminished capacity to uptake glucose, and ultimately hyperglycemia." (PMID 38755682, 2024). "This might be explained as age advances, there might be decrease in physical activity, loss of muscle mass, gain weight and the fatty cells become more resistant to insulin action leading to hyperglycemia." (PMID 38820429, 2024). "PCCs can induce metabolic derangements, including hyperglycemia by inhibiting insulin secretion." (PMID 38975526, 2024). "The presence of lectins, β-glucans, polyphenols, p-hydroxybenzoic acid, protocatechuic acid, agllic acid, cinnamic acid, p-coumaric acid, ferulic acid, chlorogenic acid, and catechin in mushrooms improves hyperglycemia by regulating insulin and glucagon secretion." (PMID 39519546, 2024). "However, thesepatients will still require close glucose monitoring to detect hypoglycemia or tosupplement with a rapid-acting insulin in case of unwanted hyperglycemia." (PMID 38224978, 2024). "Hyperglycemia was found to intensify oxidative stress in endothelial cells, and these effects could be partly reversed by administration of insulin." (PMID 39769071, 2024). "For this reason, we hypothesized that the stress response secondary to surgical anesthesia induces hyperglycemia, which affects islet cell sensitivity and leads to insulin resistance, ultimately resulting in kidney damage." (PMID 38414619, 2024). "Conventional treatment of T1D includes exogenous insulin therapy, which helps reduce hyperglycemia." (PMID 38464515, 2024). "Moreover, about 27% of patients who received the ISS required additional insulin doses to manage their uncontrolled hyperglycemia." (PMID 38698018, 2024). "Indeed, mature EndoC-βH5 cells respond to hyperglycaemia, with a pronounced increase in insulin secretion." (PMID 38161208, 2024). "Disruptions in insulin action and secretion contribute to the characteristic hyperglycaemia." (PMID 39114126, 2024). "Insufficient insulin release from pancreatic β-cells triggers hyperglycemia." (PMID 38332164, 2024).